CTLA4 (cytotoxic T-lymphocyte associated protein 4)
Diseases named in the same sentence as CTLA4 in open-access papers (continued):
Sharing a sentence is not in itself a finding about the gene and the disease.
tumor (continued). "This suggests that the KD may alter tumor-mediated T cell suppression by reducing the number of cells that are susceptible to inhibition through the PD-1 and CTLA-4 inhibitory pathways." (PMID 27178315, 2016). "Rather than targeting aberrant genomic pathways, these monoclonal antibodies (mAbs) inhibit immune regulatory checkpoints, cytotoxic T-lymphocyte-associated antigen 4 (CTLA-4) and programmed cell death protein-1 (PD-1), respectively, producing durable tumor regression in multiple tumor types." (PMID 27793177, 2016). "However, anti-CTLA-4 activity has also been linked to Fc mediated Treg depletion at the tumor site by tumor infiltrating macrophages." (PMID 28031817, 2016). "Our examination of viral and tumor antigen-specific responses revealed that the effector T cell characteristics associated with the viral response also defined the T cells responding to the encoded HER-2 tumor antigen and were further augmented in combination with CTLA-4 blockade." (PMID 26961085, 2016). "Furthermore, tumors which have a higher number of cellular mutations are more likely to respond to CTLA-4/PD-1 blockade, since there is a higher likelihood that one or more of the tumor mutations will produce a novel epitope which can be recognized by T cells." (PMID 27186886, 2016). "Intraperitoneal administration of a recombinant VSV variant targeted to Her2/neu-expressing tumours, followed by systemic CTLA-4 blockade one day later, elicited a potent anti-tumour CD4+ and CD8+ T cell response in immunocompetent mice bearing Her2/neu-positive D2F2/E2 murine mammary tumours." (PMID 26751469, 2016). "We aimed to determine if CGPs could also be applied to estimate tumor mutational load and predict clinical benefit to PD-1 and CTLA-4 checkpoint blockade therapy." (PMID 26439694, 2015). "In order to determine if the therapeutic effect of the Id2-kd N2a whole tumor cell vaccine could be enhanced, we elected to combine this therapy with immune checkpoint blockade in the form of anti-cytotoxic T lymphocyte associated antigen 4 (CTLA-4) antibody." (PMID 26079374, 2015). "Such immune activation could also be indicative for tumor-specific T-cell activation and irAE occurrence was associated with clinical response to CTLA-4 blocking in 60 % of patients." (PMID 26337719, 2015). "CTLA-4 signalling serves to limit the initiation of T cell response in the lymph nodes and PD-1 expression is associated with limiting T cell activity in the tumour microenvironment." (PMID 26371045, 2015). "The tumor microenvironment shows evidence of multiple immune-inhibitory mechanisms present concurrently such as PD-1/programmed cell death-ligand 1 (PD-L1) or cytotoxic T-lymphocyte-associated protein 4 (CTLA4) signaling as well as IDO signaling." (PMID 26674411, 2015). "The weakly immunogenic, tumor-associated antigens, which can be overexpressed self, altered self, or neoantigens, are further interwoven with unexpected pathogenic autoantigens during CTLA-4 blockade." (PMID 24904570, 2014). "The ability of CTLA-4 blockade to enhance tumor immunity may be because most tumor antigens are modified self-antigens or mutated unique antigens against which T cell cytotoxic function is believed to be relatively poor." (PMID 24855562, 2014). "Similarly, increased expression of PD-1 and CTLA-4 has been found on tumor infiltrating T cells (TIL), which can be associated with E3-ligase expression and increased Treg cells." (PMID 24987395, 2014). "Accordingly, it is speculated that extraordinary CTLA-4 expression could be associated with enhanced susceptibility to tumor growth and/or progression, attenuating the antitumor immune response." (PMID 23936819, 2013). "Particularly, if further research—focusing on the association between CTLA-4 SNPs and altered gene expression—could definitively confirm its role as a negative regulator of tumor cell proliferation." (PMID 23936819, 2013).
tumor (continued). "Interestingly, the relative loss of proliferating tumor-infiltrating CD8+ T cells in gemcitabine-treated mice was partly rescued by anti-CTLA-4." (PMID 23626745, 2013). "We observed expression of PDCD1 (which encodes PD-1) and another T cell inhibitory receptor, CTLA4, in a subset of tumor cells in the PHT and CXs from D61540, and confirmed co-expression of their protein products on the surface of tumor cells by flow cytometry." (PMID 24278200, 2013). "In addition, many tumors contain tumor-associated macrophages (TAMs) that are also suppressors of tumor immunity through production of IL-10, stimulation of Treg, and synthesis of the coinhibitory factor CTLA-4." (PMID 23056925, 2012). "Thus, our findings are consistent with earlier studies showing that the -318T allele increases the expression of CTLA-4, inhibits the activation of T lymphocytes and consequently limits the potency of tumor immunity." (PMID 17825114, 2007). "Additionally, in scenarios when PD-L1 and CTLA-4 expression is low, high tumor mutational burden (TMB) can also serve as a biomarker for immunotherapy response, with a higher TMB resulting in more neo-antigens that enhance T-cell reactivity and improve treatment outcomes." (PMID 40429725, 2025). "These monoclonal antibodies enhance T-cell activation and improve tumor suppression through disinhibiting immune response signaling components such as programmed cell death protein 1 (PD-1), programmed death-ligand 1 (PD-L1), and cytotoxic T-lymphocyte associated protein 4 (CTLA-4)." (PMID 40361386, 2025). "The TME of HNSCC typically shows high expression of inhibitory molecules such as PD-L1 on both tumor cells and immune-infiltrating cells, along with the upregulation of co-inhibitory receptors including programmed death-1 (PD-1) and cytotoxic T-lymphocyte-associated protein 4 (CTLA-4) on T cells." (PMID 41179287, 2025). "It is designed to block immunosuppressive tumor signaling by targeting receptor or ligand checkpoint proteins, with typical targets including programmed death-1 (PD-1), programmed death-ligand 1 (PD-L1), and cytotoxic T lymphocyte-associated antigen-4 (CTLA-4)." (PMID 39975599, 2025). "TIM-3 (T cell immunoglobulin domain and mucin domain-3), PD-L1 (Programmed death-ligand 1), and CTLA-4 (Cytotoxic T-lymphocyte-associated protein 4) are immune checkpoint molecules that play important roles in regulating the immune system, particularly in tumor immunity." (PMID 40430847, 2025). "ICIs, particularly those targeting the PD-1/PD-L1 and CTLA-4 pathways, have demonstrated substantial clinical benefit across a range of malignancies in the general population, particularly in tumors characterized by high mutation burden and pre-existing anti-tumor immunity." (PMID 40647389, 2025). "Similarly, CTLA-4 is expressed by T cells naturally to aid in inhibitory activities, so tumors will express the associated ligand, B7, to decrease the effectiveness of T cells against the tumor." (PMID 41180369, 2025). "Furthermore, immune checkpoints such as cytotoxic T-lymphocyte-associated protein 4 (CTLA-4) and programmed death-ligand 1 (PD-L1) are becoming recognised as important markers of the tumour microenvironment's function in the course of the disease and its reaction to immunotherapy." (PMID 40027232, 2025). "Furthermore, although we assessed immune cell infiltration and PD-1/CTLA-4 expression in the study, more immunotherapy-relevant biomarkers, such as PD-L1 and tumor mutation burden, and mechanistic analyses required to clarify the distinct immunotherapy responses of ICC and HCC components." (PMID 41211417, 2025). "Immune Checkpoint Inhibitors (ICIs), including anti-programmed cell death protein 1 (PD-1), anti-programmed death-ligand 1 (PD-L1), and anti-cytotoxic T-lymphocyte-associated protein 4 (CTLA-4), could block inhibitory signals of T cell activation to promote anti-tumor immune response." (PMID 38698843, 2024).
tumor (continued). "Thus, a better understanding of the detailed mechanism underlying anti-CTLA-4 treatment efficacy may lead to the development of drugs with fewer side effects and potent anti-tumor effects." (PMID 39106430, 2024). "In addition, FOXP3, a transcription factor that is primarily overexpressed by Tregs, is linked to elevated CTLA-4 expression and may be a sign of chemoresistance and tumor recurrence." (PMID 39456636, 2024). "ICIs can reinvigorate the anti-tumor immune response by blocking or disrupting the checkpoint protein of co-inhibitory signaling between T cells and cancer cells, such as programmed cell death (PD)-1, PD-ligand 1 (PD-L1), or cytotoxic T-lymphocyte-associated protein 4 (CTLA-4)." (PMID 39594742, 2024). "Additionally, higher tumor homogeneity in high-risk groups, potentially influencing invasiveness, was noted, with low-risk groups showing greater potential for immunotherapy response, particularly in CTLA4 positive cases." (PMID 38596689, 2024). "However, tumors exploit self-expression of these molecules, such as CTLA-4 (cytotoxic T-lymphocyte-associated protein) and PD-1 (programmed cell death protein 1), to inhibit the response of tumor-infiltrating T lymphocytes (TILs), as they are two major negative regulators of the anti-tumor response." (PMID 39091493, 2024). "The field of tumor treatment has reached a significant milestone with the introduction of immune checkpoint inhibitors (ICIs) targeting programmed cell death 1 (PD-1), programmed cell death-ligand 1 (PD-L1), and cytotoxic T-lymphocyte-associated protein 4 (CTLA-4)." (PMID 38291431, 2024). "The different mechanisms of action of anti-CTLA-4 and anti-PD-1 agents may explain the observed dissimilarities in the associations of HLA class I vs. class II tumor cell expression with therapy outcomes; however, the exact mechanisms explaining this divergence are unclear at present." (PMID 39766316, 2024). "Therefore, PCD-1/PDL1 signaling is more specific to the tumor than CTLA-4 signaling, and inhibitors of PCD-1/PD-L1 may cause less damage to healthy tissue." (PMID 36931099, 2023). "In the present study, we demonstrated that STIL expression was significantly associated with tumor immune infiltrations and promising immunotherapy targets (such as PD-L1, CTLA-4, and TIM3), indicating that targeting STIL might increase the efficacy of immunotherapy in HCC." (PMID 36899391, 2023). "In addition, immune analysis, including various bioinformatics tools, revealed significant differences in the tumor microenvironment and immune cell infiltration between the low-risk and high-risk groups, particularly the immune checkpoints PD-1, CTLA-4, and TIM3." (PMID 37198416, 2023). "In addition, programmable bacteria can be designed to selectively grow or release therapeutic payloads in response to tumor-associated stimuli, as has been demonstrated for the delivery of nanobodies against PD-L1 and CTLA-4 in the CT26 subcutaneous tumor model." (PMID 37190279, 2023). "TME further inhibits tumor-infiltrating lymphocytes (TILs) due to the presence of immunosuppressive checkpoint molecules that bind the programmed death receptor 1 (PD-1) and cytotoxic T-lymphocyte-associated antigen 4 (CTLA-4), which in turn, suppress the immune response." (PMID 36873868, 2023). "EBVaGC received significant benefit from the suggested ICI combined with CTLA-4 blockade over single immunotherapy, suggesting that tumor mutational burden and SMARCA4 mutations may be useful biomarkers for the prediction of ICI efficacy in patients with EBVaGC." (PMID 37000076, 2023). "Notably, both PD-L1 and CTLA4 are closely associated with T cell and tumor immunity." (PMID 37577750, 2023). "Mechanistically, immunoinhibitors such as cytotoxic T lymphocyte-associated molecule-4 (CTLA-4), programmed cell death receptor-1 (PD-1), and PD ligand-1 (PD-L1) act as direct negative regulators of effector cytotoxic cells, inducing immune tolerance and inhibiting anti-tumor immune responses." (PMID 37759234, 2023).
tumor (continued). "Additionally, tumor cells can upregulate the expression of checkpoint molecules, such as programmed cell death protein 1 (PD-1) and cytotoxic T-lymphocyte-associated protein 4 (CTLA-4), which can inhibit T cell activation and promote immune evasion." (PMID 37175653, 2023). "Moreover, tumor neoantigens are associated with therapeutic benefits in PD-1 or CTLA-4 blockade." (PMID 36311750, 2022). "In the SLN, by presenting soluble tumor-associated antigens from the lymph, LECs could trigger dysfunction in Cd8+ T cell and increase T-cell apoptosis by regulating the expression of Pd-1, Cd80 and cytotoxic T-lymphocyte associated protein 4 (Ctla4)." (PMID 36266717, 2022). "Therapies with immune checkpoint inhibitors (ICI) targeting cytotoxic T-lymphocyte-associated antigen 4 (CTLA-4), programmed cell death protein 1 (PD-1), and programmed cell death ligand 1 (PD-L1) are associated with increased T cell activation and effective anti-tumor immune responses." (PMID 35056392, 2022). "The commonly used inhibitors against a variety of tumour types consist of therapeutic monoclonal antibodies, such as pembrolizumab and ipilimumab, targeting the IC pathways of programmed cell death 1 (PD-1) and cytotoxic T-lymphocyte-associated protein 4 (CTLA-4), respectively." (PMID 35595321, 2022). "In addition, eTregs express immune checkpoint molecules, such as cytotoxic T-lymphocyte-associated protein 4 (CTLA-4) and programmed cell death-1 (PD-1), suggesting that controlling tumor-infiltrating Tregs may be a potential target for cancer immunotherapy." (PMID 35438346, 2022). "The addition of OX40/TLR3/9 immunotherapy to SBRT resulted in local depletion of Tregs and tumor macrophages and reduced Treg-associated gene expression (FoxP3), suppressed macrophage-associated gene expression (IL-8), and suppressed exhausted T cell-associated gene expression (CTLA4)." (PMID 35055015, 2022). "It is now generally believed that the mechanism of tumor immune escape is the persistent chronic immune stimulation caused by tumor antigens, exhausting T cells and losing most of their effector properties, and the exhausted T cells upregulate PD-1, CTLA-4, LAG-3, and other immune checkpoints." (PMID 36612165, 2022). "Combined CTLA-4 and PD-1 blockade has been associated with more antitumor responses, one possible rationale being ipilimumab therapy increases tumor-infiltrating T cells and upregulates PD-1/PD-L1 inhibitory pathway in a compensatory fashion indicating that combination therapy may be more efficient." (PMID 34063238, 2021). "Furthermore, tumor cell-extrinsic STAT3 activation also regulates the immune tolerance and suppression of anti-tumor immunity by upregulating the expression of immune checkpoint proteins (e.g., PD1, CTLA4) on the surface of tumor-associated myeloid cells, B-cells, Tregs, and CD4 and CD8 T-cells." (PMID 34944848, 2021). "Furthermore, recent work has revealed that RIG-I is required for adequate response to anti-CTLA-4 treatment by inducing caspase-3-mediated tumor cell death, following which the tumor-associated antigens are processed and presented, leading to a robust CD8+ T cell-mediated adaptive immune response." (PMID 33572196, 2021). "Considering that patients with high expression of CTLA-4 was more likely to benefit from immunotherapy of anti-CTLA-4, and that anti-TIM-3 or anti-CTLA-4 could enhance tumor immunity, we speculated that patients in the low-risk group may be more sensitive to CTLA-4 and TIM-3 inhibitors." (PMID 34497605, 2021). "The disturbance of the immune system is critical in tumor development, such as the disruption of immune checkpoints like programmed cell death protein 1/programmed cell death protein 1 ligand 1 (PD-1/PD-L1) or cytotoxic T lymphocyte-associated protein-4 (CTLA-4)." (PMID 35096962, 2021). "Therefore, tumor mutation burden might be one of the biomarkers of PD-1/PD-L1 combined with CTLA-4 treatment." (PMID 33716732, 2021).
tumor (continued). "Immunotherapy and modulation of the tumor microenvironment are rapidly developing fields of interest in gynecologic oncology translational research; examples include the PD-1 (programmed cell death 1) and CTLA-4 (cytotoxic T-lymphocyte-associated protein 4) axes and the Wnt pathway." (PMID 33918476, 2021). "Thus, sCD80 may bind to CTLA4 and initiate T cell co-inhibition, which could lead to immune escape of tumor cells and elevated risk of recurrence." (PMID 32909077, 2021). "Interestingly, we observed a significant increase in CTLA-4 expression in CD4+ T cells co-cultured with STING deficient tumor cells compared to WT, which may be due to alternative compensatory pathways." (PMID 33995649, 2021). "In addition to dysfunctional stromal cells in the tumor microenvironment, there are also various regulatory T-cells, myeloid-derived suppressor cells, and up-regulated tumor suppressor molecules such as cytotoxic T-lymphocyte-associated antigen-4 (CTLA-4) and programmed cell death protein-1 (PD-1)." (PMID 34525966, 2021). "Therefore, the tumor mutational burden may be useful to identify patients who could take advantage of PD-1 and CTLA-4 blockade combination immunotherapy." (PMID 34638281, 2021). "Cytotoxic T-lymphocyte-associated antigen 4 (CTLA-4), programmed death 1 (PD-1), and its ligand (PD-L1), as well as the B7 family of immune checkpoints, could be considered to be the main immunotherapy targets to inhibit tumor growth in a variety of cancers." (PMID 34572263, 2021). "Vaccinia virus encoding both IL-7 and IL-12 completely changed the tumor immune microenvironment by boosting the inflammatory immune status, which showed beneficial systemic antitumor efficacy and markedly improved the sensitivity of solid tumors to systemic anti-PD-1 and anti-CTLA4." (PMID 34692696, 2021). "Furthermore, tumor cells can escape the anti-cancer immunity by activating regulatory T lymphocytes that express cytotoxic T-lymphocyte-associated protein 4 (CTLA-4) competing with CD28 of effector T lymphocytes for binding to CD80/CD86 of antigen presenting cells." (PMID 32610582, 2020). "Among these mechanisms, upregulation of PD1, CTLA4, etc. on the T-cell surface and conversion of T cells to Tregs has emerged as an important contributor, which is reflected in decreased effector T cells in response to tumor antigens, thus causing failure of therapy and tumor progression." (PMID 32582141, 2020). "Tumor types with low Treg density might associate with effective therapeutic efficacy mediated by CTLA4 blockade, but further studies such as comparison of pre- and post-treatment Treg densities in different kinds of tumor types are required to elucidate this hypothesis." (PMID 32937841, 2020). "Interestingly, we found that ALDH3A2 co-expression might be negatively correlated with the PDCD1, PDCD1LG2, and CTLA4 genes, and positively associated with tumor purity." (PMID 33148208, 2020). "Hence, the discovery of co-inhibitory receptors such as Cytotoxic T-Lymphocyte-associated Antigen 4 (CTLA-4) or Programmed Death-1 (PD-1) brought new possibilities to activate immune response against tumor cells using monoclonal antibodies to such co-inhibitory immune checkpoints." (PMID 32344813, 2020). "Programmed cell death 1 (PD‐1), programmed death ligand‐1 (PD‐L1) and Cytotoxic T‐lymphocyte‐associated protein‐4 (CTLA‐4) could inhibit the proliferation and differentiation of immunocompetent cells and the recognition of tumour cells by tumour‐infiltrating lymphocytes (TILs)." (PMID 33145941, 2020). "Tumoral PD-L1(+)/immune cell PD-L1(−)/CD8+/low TILs showing a worse prognosis may be beneficial for combinatorial therapies of anti-PD-L1/PD-1 and anti-cytotoxic T-lymphocyte associated antigen 4 (CTLA4) that would promote effector T cells, thus attack the tumor." (PMID 32498695, 2020).